CAMK2N1 (calcium/calmodulin dependent protein kinase II inhibitor 1)
Diseases named in the same sentence as CAMK2N1 in open-access papers (continued):
Sharing a sentence is not in itself a finding about the gene and the disease.
lung carcinoma (2 papers, 2020 to 2025). "Overexpression of CAMK2N1 in lung cancer cells inhibits cancer cell proliferation and metastasis and increases cell death mechanisms." (PMID 40867253, 2025). "Although the tumor suppressor CAMK2N1 (Calcium/Calmodulin Dependent Protein Kinase II Inhibitor 1) has not been associated with lung cancer yet, its hypermethylation has been shown to promote tumorigenesis in other cancers." (PMID 32899191, 2020). "In lung cancer, calcium/calmodulin-dependent protein kinase II (CAMK2) inhibitor 1 (CAMK2N1) is a tumour suppressor gene which acts through inhibition of the Akt/mTOR pathway." (PMID 40867253, 2025).
metabolic syndrome (2 papers, 2019 to 2024). A cluster of metabolic risk factors for CARDIOVASCULAR DISEASES and TYPE 2 DIABETES MELLITUS. "Camk2n1 regulates multiple organ systems associated with metabolic syndrome, and its ablation improved MetS features in spontaneously hypertensive rat." (PMID 31327268, 2019). "Camk2n1 regulates multiple networks that control metabolic syndrome traits and merits further investigation as a therapeutic target in humans." (PMID 31327268, 2019). "Therefore, we knocked out Camk2n1 in spontaneously hypertensive rat to investigate its role in metabolic syndrome." (PMID 31327268, 2019).
multiple myeloma (2 papers, 2021 to 2025). "In addition, N6-methyladenosine-induced miR-182-5p was also able to promote multiple myeloma by regulating CAMK2N1, which in turn promotes multiple myeloma." (PMID 40949143, 2025).
Obesity (2 papers, 2019 to 2024). Accumulation of substantial excess body fat. "WGCNA of the adipose transcriptome defined CaMKII-independent alterations in obesity- and MetS-related cell cycle, classical complement, and apoptosis pathways in Camk2n1−/− rats." (PMID 31327268, 2019).
prostate tumor (2 papers, 2013 to 2014). "Encouraged by these observations, we then investigated the role of CAMK2N1 in inhibiting prostate tumor growth in vivo." (PMID 25003983, 2014). "The nuclear CAMK2N1 staining was quantified in human prostate tumors (n = 50), hyperplastic tissues (n = 20), and normal control specimens (n = 10)." (PMID 25003983, 2014). "Reduced CAMK2N1 expression positively correlated with prostate tumor progression (stage, TNM)." (PMID 25003983, 2014). "To determine the mechanisms by which CAMK2N1 functions to inhibit prostate tumor growth, we performed genome-wide gene expression analysis using human 12×135K gene expression array by comparing DU145 cells with or without CAMK2N1 overexpression (> 1.5-fold and p < 0.05)." (PMID 25003983, 2014).
Alzheimer disease (1 paper, 2022). A progressive, neurodegenerative disease characterized by loss of function and death of nerve cells in several areas of the brain leading to loss of cognitive function such as memory and language. "In the brain, Alzheimer’s disease and memory-related genes (Camk2n1, Apod, and Serpina3n), and immune-response-related genes (Spp1, CD68, GFAP, Mpeg, Ddx3y, Lyz2, CTSZ, Tyrobp, C4b, and C1qa), were selected for mRNA qPCR analysis in adenine-induced CKD mice." (PMID 35447931, 2022).
coronary artery disease (1 paper, 2019). "In human visceral fat, we found that CAMK2N1 expression correlated with fat mass and body mass index, in keeping with previous reports of 34 cis-eQTLs (GTex Portal) that associated significantly with increased CAMK2N1 expression and elevated risk of T2DM and coronary artery disease." (PMID 31327268, 2019).
Hypertension (1 paper, 2019). The presence of chronic increased pressure in the systemic arterial system. "Camk2n1 knockout in SHR, ameliorated multiple pathophysiological phenotypes including hypertension, LV mass, insulin sensitivity, and visceral adiposity, associated with reduced cardiorenal CaMKII activity and independent of adipose CaMKII activity." (PMID 31327268, 2019).
Insulin resistance (1 paper, 2019). Increased resistance towards insulin, that is, diminished effectiveness of insulin in reducing blood glucose levels. "Camk2n1 deficiency reduced insulin resistance, visceral fat, and adipogenic capacity through the altered cell cycle and complement pathways, independent of CaMKII." (PMID 31327268, 2019). "Insulin resistance, a key factor in MetS, was ameliorated in Camk2n1−/− rats and occurs independently of CaMKII in adipose tissue." (PMID 31327268, 2019). "Plasma insulin concentrations at t0 and t30–t60 minutes and area under the insulin curve following glucose bolus were significantly reduced together with homeostatic model assessment of insulin resistance (SHR, 1.22±0.06, Camk2n1−/−, 0.51±0.06, P=0.00001) in Camk2n1−/− compared with SHR." (PMID 31327268, 2019).
memory impairment (1 paper, 2017). "In this case, the retrieval-induced increase T286 autophosphorylation and GluaA1 levels observed after CaMK2N1 knockdown might result in memory impairment due to blocking of memory destabilization." (PMID 28642476, 2017). "That being the case, the compensation was not enough to avoid the retrieval-induced memory impairment after CaMK2N1 knockdown." (PMID 28642476, 2017).
meningioma (1 paper, 2017). A generally slow growing tumor attached to the dura mater. "The trends of gene expression profiles of candidates such as EFCAB2, EPS8L1, NOL3, PAIP1 and SNX1 showed elevated expression in meningiomas compared to controls, while CAMK2N1, CRYM and PRPSAP2 showed decreased expression levels in meningiomas compared to the controls." (PMID 28938569, 2017).
metastatic prostate carcinoma (1 paper, 2023). A carcinoma that arises from the prostate gland and has spread to other anatomic sites. "For instance, CAMK2N1, which is upregulated in locally invasive and metastatic prostate cancer, has been identified as an EMT-related gene with implications in cancer progression." (PMID 37907576, 2023).
neuropathy (1 paper, 2023). A disorder affecting the nervous system that manifests with pain, tingling, numbness, and/or muscle weakness. "Although significant associations were found between SNPs in ABCA1 (rs2230806), ABCC2 (rs1885301, rs3740066, rs4148396) and CAMK2N1 (rs12023000) and CIPN in univariate analyses, none of these SNPs were associated with neuropathy in multivariate setting." (PMID 36672910, 2023).
squamous cell carcinoma (1 paper, 2023). A carcinoma arising from squamous epithelial cells. "One previous study demonstrated that the upregulated DEG CAMK2N1 is linked with poor OS and progression-free interval (PFI) of high-risk squamous cell carcinoma patients." (PMID 38025757, 2023).
type 2 diabetes mellitus (1 paper, 2019). A type of diabetes mellitus that is characterized by insulin resistance or desensitization and increased blood glucose levels. "We analyzed human data from the GTEx and Type 2 Diabetes Knowledge Portals to investigate whether sequence variants that increase/decrease CAMK2N1 expression were associated with cardiometabolic traits." (PMID 31327268, 2019).
tumor (40 papers, 2010 to 2025). "Conversely, tumor suppressor pathways mediated by miR-323/p73 and miR-129-5p/CAMK2N1 have been associated with increased sensitivity to DTX." (PMID 41018319, 2025). "In summary, our results suggest that the ncRNA-mediated high expression of CAMK2N1 is associated with poor prognosis and tumor immune infiltration of GC." (PMID 36092901, 2022). "In the xenograft tumor model, CAMK2N1 knockdown remarkably abolished the PRMT5 loss-induced growth inhibition of PC-3 xenografts." (PMID 35624451, 2022). "Nevertheless, subsequent functional analyses identified tumor suppressive functions for CAMK2N1 and a dichotomous role for RUNX3 transcript variants regulated by DNA methylation." (PMID 33482905, 2021). "Furthermore, CAMK2N1 levels were significantly negatively associated with tumor immune cell infiltration, biomarkers of immune cells, and immune checkpoint expression." (PMID 36092901, 2022). "CAMK2N1 has been recognized as a tumor suppressor that downregulates the β-catenin/c-Myc oncogenic signaling pathway." (PMID 40949143, 2025). "Circ-IP6K2 downregulates the tumor suppressor CAMK2N1 in ccRCC by activating the miR-1292-5p/CAMK2N1 axis, inhibiting the proliferation, migration and invasion of tumor cells in vitro." (PMID 41181710, 2025). "Molecules with tumor suppressor functions such as CAMK2N1, CDH1, IGFBP4, RGS2, and WNT5A were upregulated in MDA231 cells after their co-culture with DBMSCs in an IC setting." (PMID 39768220, 2024). "The expression of CAMK2N1 was obviously increased when DNMT1 expression was markedly reduced in tumor tissues." (PMID 36755811, 2023). "These include the CYGB gene encoding cytoglobulin, which is a known inhibitor of mitosis and the calcium/calmodulin dependent protein kinase II inhibitor 1 gene (CAMK2N1) that can act as a tumour suppressor and block metastasis." (PMID 37276213, 2023). "Inhibition of CAMK2N1 significantly enhanced the migration and invasion of PCa cells and xenograft tumor growth, while the knockdown of DNMT1 reversed these effects." (PMID 36755811, 2023). "Nevertheless, the T4 tumor or Gleason score 10 tumor still has a slightly higher methylation level of CAMK2N1." (PMID 36755811, 2023). "To further explore the role of CAMK2N1 in tumor immune, we evaluated the expression correlation of CAMK2N1 with biomarkers of immune cells in GC using the GEPIA database." (PMID 36092901, 2022). "CAMK2N1 has been widely recognized as a bona fide tumor suppressor due to its crucial role in attenuating tumorigenesis and PCa progression." (PMID 35624451, 2022). "The risk heatmap indicates that TRIML2, CAMK2N1, and DKK1 were upregulated in the high-risk cluster, suggesting their tumor-promoting role." (PMID 36685979, 2022). "The downstream target of miR-182-5p, CAMK2N1, acts as a tumor suppressor, through which this miRNA controls the growth, proliferation and colony formation abilities in OSCC." (PMID 36531016, 2022). "To sum up, we found that ncRNA-related upregulation of CAMK2N1 correlates with poor prognosis and tumor immune infiltration of patients in GC." (PMID 36092901, 2022). "EOC patients with methylation of CAMK2N1 or RUNX3 have a shorter overall survival than patients without methylation of these genes independently from FIGO staging or tumor resection status." (PMID 33482905, 2021). "Globally, these results indicate that increased expression of those EMT-related genes occurs along tumor progression, which is further underscored by the finding of increased CAMK2N1 and WNT5A immunoexpression in metastatic PCa." (PMID 31762801, 2019). "CAMK2N1 expression has tumor-suppressing roles, such as depressed cell proliferation and cell cycle arrest in certain cancers 37-39." (PMID 31598163, 2019). "The inhibition of tumor growth by expressing CAMK2N1 established a role of CAMK2N1 as a therapeutic target." (PMID 25003983, 2014).
tumor (continued). "Recurrent patients with high AR levels had an improved recurrence-free survival if their tumor also expressed high CAMK2N1 protein levels." (PMID 25296973, 2014). "TUNEL staining was conducted to assess the effect of CAMK2N1 on cell apoptosis in tumor samples from in vivo experiment." (PMID 25003983, 2014). "We observed that that overexpression of CAMK2N1 significantly reduced both the tumor size and the tumor weight." (PMID 25003983, 2014). "Similarly, the reduction of CAMK2N1 expression also inhibited the tumor suppressive effect of DNMT1 knockdown." (PMID 36755811, 2023). "Our findings suggest that tumor immune infiltration may be partly responsible for the carcinogenic effect of CAMK2N1-mediated GC." (PMID 36092901, 2022). "In a platinum-sensitive OC cohort mostly comprised of patients with HGSC, the combination of CAMK2N1 (calcium/calmodulin dependent protein kinase II inhibitor 1) and RUNX3 (RUNX family transcription factor 3) methylation in tumor specimens was associated with shorter OS and PFS." (PMID 35406435, 2022). "Thus, considering the actions mediated by CAMK2, a tumor suppressor role would be expected for CAMK2N1." (PMID 31762801, 2019). "Previously, a study demonstrated the tumor suppressive effect of Camk2n1." (PMID 31330819, 2019). "CAMK2N1, whose transcript levels are increased in primary PC yet downregulated in CRPC and whose downregulation predicts poor clinical outcome, encodes functions that suppress tumor invasiveness and androgen-independent proliferation." (PMID 28055971, 2017). "The silencing of CAMK2N1 expression increases tumor growth and cell cycle progression." (PMID 25789025, 2015). "Increased CAMK2N1 expression suppressed cell proliferation, survival and tumor growth in vivo." (PMID 25003983, 2014). "Since elevated cell death may also contribute to impaired tumor growth, we determined whether CAMK2N1 induces apoptosis by Annexin V staining and TUNEL assays." (PMID 25003983, 2014). "The CAMK2N1 gene, cloned and characterized as an inhibitor of CaMKII (calcium/calmodulin-dependent protein kinase II), has been shown to affect tumorigenesis and tumor growth." (PMID 25003983, 2014). "Since elevated cell death may also contribute to impaired tumor growth, we determined whether CAMK2N1 induces apoptosis through AR by Annexin V staining assays." (PMID 25296973, 2014). "Similarly, the percentage of apoptotic cells was increased in CAMK2N1 overexpressing tumor derived from nude mice implanted with DU145 cells." (PMID 25003983, 2014). "Reducing expression of CAMK2N1 will accelerate tumor growth." (PMID 21114830, 2010). "In addition, our current findings also indicated that CAMK2N1 might play its oncogenic roles through decreasing tumor immune cell infiltration and immune checkpoint expression." (PMID 36092901, 2022). "However, the mechanism through which CAMK2N1 promotes tumor aggressiveness remains unclear and require functional studies." (PMID 31762801, 2019). "Among them, upregulated genes such as CAMK2N1, IGFBP4, RGS2, WNT5A, and CDH1 have both tumor suppressor and inhibitory effects on EMT." (PMID 39768220, 2024). "The eight genes (CAMK2N1, WNT7A, F2RL1, AREG, DEFB1, CNFN, TGFBI, and CAV1) included in the signature have been extensively studied and are known to be involved in tumor progression and EMT process." (PMID 37907576, 2023). "According to the mechanism of miRNA, these miRNAs which bind to CAMK2N1 should be tumor-suppressive miRNAs, and these miRNAs which bind to FMO5 are tumor-promoting." (PMID 36092901, 2022). "Specifically, the genes of the identified best methylation marker combination CAMK2N1 and RUNX3 were shown to have tumor suppressive functions (CAMK2N1) or to be involved in platin resistance and migration (RUNX3)." (PMID 33482905, 2021). "CAMK2N1, one of two endogenous CAMKII inhibitors, was firstly identified as tumor suppressor inducing cell cycle arrest by p27 stabilization." (PMID 33482905, 2021).
tumor (continued). "Four genes, CAMK2N1, CGNL1, DLC1 and SYT11, the expression of which was lower in the tumor tissues than in the normal tissues, were enriched in the cell junction." (PMID 25789025, 2015). "To determine the expression of CAMK2N1, AR, pAKTser473, PSA, Bax, Bcl-2, p21, and Ki67 in tumor tissues, we conducted qRT-PCR and IHC staining in tumors." (PMID 25296973, 2014). "To further support our hypothesis, we collected FFPE prostate tissues to measure the DNA methylation level of CAMK2N1 between benign samples from 16 BPH patients and tumor samples from 52 PCa patients." (PMID 36755811, 2023). "Neuron functional genes such as CaMK2N1, MEG3, SNCB, SYT1, DKK3 are almost expressed in the marginal area of the tumor (not shown)." (PMID 39257581, 2024). "Other genes, CAMK2N1 and ALDH1A3, showed no change or only minimal upregulation in the tumor tissues." (PMID 25789025, 2015).
cancer (14 papers, 2015 to 2025). A tumor composed of atypical neoplastic, often pleomorphic cells that invade other tissues. "CAMK2N1 was identified, which was highly expressed in high M-stage cancers and significantly correlated with poor prognosis of HCC." (PMID 40949143, 2025). "Recent studies revealed that the expression level of CAMK2N1 is also involved in the tumorigenesis of human cancers." (PMID 36092901, 2022). "Increasing evidence has demonstrated that CAMK2N1 plays a key role in the proliferation and progression of multiple human cancers." (PMID 36092901, 2022). "Risk signature contigs mapped at least five other genes with established driver roles in PCa or other cancers: CAMK2N1, COL1A1, GTSE1 and PTPRN2, supporting the relevance of these sequence contigs in PCa etiology." (PMID 33845808, 2021). "Another web-based tool, KM plotter, shows that CAMK2N1 either worsens or improves survival in various cancer types." (PMID 34442426, 2021). "Yet, the mapped genes were highly relevant to PCa etiology and included known cancer drivers LDLRAD4, GMNN, COL1A1, CD38, PTPRN2, GTSE1 and CAMK2N1 in the risk signature and KLK2, AR, KLK3, SPDEF in the relapse signature." (PMID 33845808, 2021). "Thus, the inhibitory activity of CAMK2N1 on CAMK2 in PCa would provide conditions for cancer cells to endure EMT through slowing cellular proliferative activity." (PMID 31762801, 2019). "Further cellular assays showed that CAMK2N1 expression was downregulated in HCC cells, and its knockdown increased the proliferation, migration, and invasion levels of cancer cells." (PMID 40949143, 2025). "There have been no studies examining CAMK2N1 and methylation in cancer." (PMID 25789025, 2015).
CAMK2N1 also shares sentences with these, for which no sentence is quoted: hepatocellular carcinoma (5 papers); renal cell carcinoma (3); breast carcinoma (2); glioma (2); bladder cancer (1); brain tumors (1); cardiac hypertrophy (1); cardiovascular diseases (1); Ewing sarcoma (1); fibromatosis (1); head and neck cancer (1); heart failure (1); liver cancer (1); lung diseases (1); osteosarcoma (1); serous ovarian cancer (1); thyroid cancer (1).